SLC26A4 (solute carrier family 26 member 4)
Diseases named in the same sentence as SLC26A4 in open-access papers (continued):
Sharing a sentence is not in itself a finding about the gene and the disease.
cancer (9 papers, 2012 to 2026). A tumor composed of atypical neoplastic, often pleomorphic cells that invade other tissues. "Pan-cancer analysis focusing on SLC26A4 found that it was differentially expressed in most cancer types." (PMID 35836192, 2022). "Thus, the expression patterns and location of SLC26A4 along with cancer types show potential for diagnosis of cancers." (PMID 38673775, 2024). "Assuming that thyroid tissue is de-differentiating upon carcinoma development, this might be a plausible mechanism by which SLC26A4 and TG are downregulated in FTC." (PMID 27329729, 2016). "Notably, TPO, DIO1, and SLC26A4 were consistently downregulated in both cancer subtypes." (PMID 40746809, 2025). "Functionally, IGF2BP2 promotes proliferation, suppresses thyroid differentiation genes (TSHR, SLC26A4, SLC5A5, TPO, PAX8, FOXE1, and NKX2.1), and enhances cancer stemness." (PMID 41522349, 2026). "We identified five genes (KCNJ16, SLC26A4, TG, TPO, and SYT1) as potential cancer treatment targets." (PMID 37208644, 2023). "Previous studies have mostly believed that SLC26A4 plays a vital role in maintaining normal hearing and never explored its significance in malignancies." (PMID 35836192, 2022).
tumor (6 papers, 2004 to 2024). "SLC26A4 plays a role not only in non-tumor cells but also in tumor cells." (PMID 38673775, 2024). "To mitigate this, we classified normal TFCs using 3 additional markers (i.e., TFF3, TPO, SLC26A4) that were previously shown to be expressed in normal thyroids but not in tumor cells." (PMID 37053016, 2023).
inherited diseases (4 papers, 2015 to 2024). "Enlarged vestibular aqueduct is an autosomal genetic disease mainly caused by mutations in the SLC26A4 gene and includes non-syndromic and syndromic types." (PMID 37745850, 2023).
SLC26A4 also shares sentences with these, for which no sentence is quoted: Hearing impairment (27 papers); Enlarged vestibular aqueduct (5); Usher syndrome (4); diastrophic dysplasia (3); Hypertension (3); Waardenburg syndrome (3); auditory neuropathy (2); congenital sensorineural deafness (2); endolymphatic hydrops (2); follicular thyroid carcinoma (2); phenylketonuria (2); acute respiratory distress syndrome (1); age (1); airway hyperresponsiveness (1); Alpha-thalassemia (1); Alport syndrome (1); athyreosis (1); autism spectrum disorder (1); Bardet-Biedl syndrome (1); Bartter syndrome type 4 (1); benign adenoma (1); branchio-oto-renal syndrome (1); breast invasive carcinoma (1); Calcium oxalate nephrolithiasis (1); cervical cancer (1); cervical squamous cell carcinoma (1); chondrodysplasia (1); chronic rhinosinusitis with nasal polyps (1); CMV infection (1); colon adenocarcinoma (1).
A further 61 diseases each share a sentence with SLC26A4 in 1 paper.